NLK (nemo like kinase)
Diseases named in the same sentence as NLK in open-access papers (continued):
Sharing a sentence is not in itself a finding about the gene and the disease.
prostate carcinoma (6 papers, 2013 to 2023). A carcinoma that arises from epithelial cells of the prostate gland. "In prostate cancer metastases, the expression of NLK was found to be reduced, and increasing NLK expression induced apoptosis in cultured cells." (PMID 37627077, 2023). "Taken together, these evidences suggest that CBP is likely to be an important direct target of NLK in the regulation of Nurr1 expression in prostate cancer." (PMID 27036119, 2016). "NLK expression was inversely correlated with Nurr1 expression in prostate cancer tissues and cell lines." (PMID 27036119, 2016). "It has been shown that within prostate cancer cells, wild-type AR physically interacts with Nemo-like kinase (NLK) and that NLK is able to regulate the activity and transcription of AR in this context." (PMID 26308581, 2015). "Contrasting these results, in prostate cancer cells, endogenous NLK were localized in the nucleus (LNCaP), but the wildtype NLK expression in LNCaP cells also directed NLK to the nucleus." (PMID 24816797, 2014). "Notably, NLK was observed to actively regulate androgen receptor signaling within prostate cancer cells." (PMID 37627077, 2023). "It was previously reported that NLK could interact with the wild-type AR in prostate cancer cell lines." (PMID 26308581, 2015). "This discrepancy may be explained by cell type specificity as well as androgen-mediated receptor activation, both proved to be essential for NLK localization in prostate cancer cells." (PMID 24816797, 2014). "Furthermore, overexpression of NLK prompted a more effective induction of apoptosis in AR-expressing prostate cancer cells than in AR-negative cells." (PMID 24816797, 2014). "Our results suggest that NLK inhibits transcriptional activation of Nurr1 gene by impeding CBP’s role as a co-activator of NF-κB and CREB in prostate cancer." (PMID 27036119, 2016). "In prostate cancer, overexpression of NLK induced apoptosis in AR-expressing prostate cancer cells, but not in AR-negative cells." (PMID 24816797, 2014).
colon carcinoma (5 papers, 2013 to 2023). "Previous studies have suggested that NLK overexpression induced apoptosis in human colon cancer cells." (PMID 23935942, 2013). "Interestingly, in colon cancer cell lines, we found that increasing intracellular miR-195-5p was able to reduce the protein expression levels of NLK, LEF1 and Cyclin D1 via JUP modulation." (PMID 38069408, 2023). "Jun Yasuda proposed that NLK might function as a tumor suppressor in colon cancer by inhibiting the Wnt/β-catenin pathway, which suppresses the transcriptional activity of the β-catenin/T-cell factor (TCF) complex by phosphorylating TCF." (PMID 23935942, 2013). "Among the top 10 regulatory kinases, only CHEK2 and nemo-like kinase (NLK) had a significant impact on outcome in patients with rectal cancer; of note, none of these kinases had a significant influence on the outcome of patients with colon cancer." (PMID 36164349, 2022).
glioblastoma (5 papers, 2015 to 2024). The most malignant astrocytic tumor (WHO grade IV). "Moreover, HOTAIR suppressed the β-catenin pathway, leading to cell cycle arrest and repression of invasion, putatively by downregulating Nemo-like kinase (NLK) in glioblastoma." (PMID 34322395, 2021).
Diamond-Blackfan anemia (3 papers, 2020 to 2025). A congenital aregenerative and often macrocytic anemia with erythroblastopenia. "For example, in patients with Diamond Blackfan anemia (DBA), the expression of miR-26a is increased in response to metformin, leading to the blockade of Nemo-like kinase (NLK kinase) and promotion of erythroid differentiation." (PMID 41439991, 2025).
gallbladder cancer (3 papers, 2015 to 2024). "Study have shown that NLK overexpression in gallbladder cancer is significantly correlated with TNM stage and perineural invasion, leading to a worse prognosis." (PMID 39097735, 2024). "Our results are supported by recent reports that NLK expression is significantly up-regulated in human hepatocellular and gallbladder carcinoma cells and that targeted disruption of NLK results in suppression of cell growth and cell cycle transition arrest." (PMID 26503334, 2015).
laryngeal carcinoma (3 papers, 2015 to 2020). Carcinoma that arises from the laryngeal epithelium. "Aberrant expression of NLK has been associated with the initiation or progression of oral squamous cell carcinoma, laryngeal cancer, non-small-cell lung cancer (NSCLC), and CRC." (PMID 32605309, 2020). "In human laryngeal carcinoma, tissue down-regulation of NLK inhibited tumour cell proliferation and invasion, suggesting that NLK might be used as a potential molecular target for development and diagnosis of laryngeal carcinoma." (PMID 33276680, 2020).
lung carcinoma (3 papers, 2015 to 2022). "Metformin treatment decreased NLK expression and recapitulated the phenotype observed by NLK knockdown, indicating that NLK may be a contributing factor and underlying mechanism for the inhibition of growth and stemness observed in lung cancer cells." (PMID 26503334, 2015). "The identification of NLK in such a significant number of NSCLC tissue samples prompted us to examine NLK protein levels in multiple human lung cancer cell lines." (PMID 26503334, 2015). "In order to examine the effect of NLK depletion on lung cancer cell tumorigenicity in an in vivo model, we inoculated A549, A549-scramble and A549-shRNA cells subcutaneously into the left flank of female athymic nude mice." (PMID 26503334, 2015).
neuroblastoma (3 papers, 2021 to 2025). Neuroblastoma (NB) is the most common solid, extracranial childhood tumor. "Poor prognosis of a number of carcinomas, osteosarcomas, and neuroblastomas has all been attributed to elevated NLK expression." (PMID 34298020, 2021). "NLK is upregulated and correlated with poor prognosis in non–small-cell lung carcinoma and small-cell lung carcinoma, colorectal cancer, hepatocellular carcinoma, laryngeal cancer, osteosarcoma, and neuroblastoma." (PMID 34298020, 2021). "In neuroblastoma, miR-221 enhances mycn protooncogene, bhlh transcription factor (MYCN) oncoprotein levels by targeting Nemo-like kinase (NLK), a negative regulator of MYCN; high miR-221 expression correlates with advanced disease and poor prognosis." (PMID 41369385, 2025).
ovarian carcinoma (3 papers, 2015 to 2023). A malignant neoplasm originating from the surface ovarian epithelium. "Similar studies confirm that NLK is a tumor suppressor gene in ovarian cancer." (PMID 31294654, 2019).
viral infection (3 papers, 2019 to 2025). "NLK deficiency rendered the cells resistant to viral infection and resulted in a considerably lower percentage of GFP-positive cells than that in the wild-type cell population." (PMID 31324787, 2019). "We found markedly enhanced SeV-induced IRF3 phosphorylation and dimer formation in NLK−/− cells compared with those in wild-type cells after viral infection, indicating that NLK regulates SeV-induced IRF3 signaling." (PMID 31324787, 2019). "Here, we show that NLK inhibits the antiviral immune response during viral infection by targeting MAVS for degradation." (PMID 31324787, 2019). "Interestingly, NLK exhibited a band similar to that of MAVS following viral infection, which implies that NLK is present in the prion-like complex together with MAVS after viral infection." (PMID 31324787, 2019). "NEMO-like kinase (NLK), a host enzyme, modulates the balance of the IFN and NF-κB signaling pathways to maintain host homeostasis during viral infections." (PMID 36560803, 2022). "Although most endogenous NLK was located in the nucleus, NLK in the cytosol colocalized very well with MAVS, and this colocalization was especially enhanced in MAVS prion-like aggregates after virus infection." (PMID 31324787, 2019).
Brain atrophy (2 papers, 2022 to 2024). Partial or complete wasting (loss) of brain tissue that was once present. "Overexpression of NLK via adeno-associated virus (AAV) injection into the striatum of N171-82Q mice leads to decreased brain atrophy, increased dopamine- and cAMP-regulated neuronal phosphoprotein (DARPP32) expression and decreased mtHTT aggregates." (PMID 36009526, 2022). "On the contrary, NLK haploinsufficiency in HdhQ250 mice showed increased brain atrophy and mtHTT levels as well as decreased DARPP32." (PMID 36009526, 2022).
colitis (2 papers, 2019 to 2020). Inflammation of the colon. "The results indicated that SSW controlled the ubiquitin-proteasome system activation to limit ubiquitination of the NEMO/NLK signaling pathway in TNBS-induced colitis." (PMID 30894816, 2019). "After rats were treated with TNBS three times, NEMO protein was ubiquitinated and highly expressed, while NLK ubiquitination was inhibited in the damaged colonic mucosa of rats with untreated colitis." (PMID 30894816, 2019). "In TNBS-induced colitis, the colonic mucosa had markedly increased expression of ubiquitinated IKKγ, E1, E2, and E3 compared with normal colonic mucosa, while ubiquitinated NLK level was downregulated." (PMID 30894816, 2019). "In the present study, expression of ubiquitinated IKKγ (NEMO), NF-κB P65, and NLK was inhibited in the colonic mucosa of rats with experimental colitis treated by SSW, while the levels of E1, E2i, and E3 were decreased, and synchronously the phosphorylation of TAK1 and P38 was limited." (PMID 30894816, 2019). "In the present study, colonic mucosa from rats with TNBS-induced colitis had increased levels of ubiquitinated IKKγ (NEMO), NF-κB P65, and NLK and decreased level of ubiquitinated NLK." (PMID 30894816, 2019). "However, the level of NLK protein was not obviously changed after treatment of colitis with SSW." (PMID 30894816, 2019).
Huntington disease (2 papers, 2020 to 2025). Huntington disease (HD) is a rare neurodegenerative disorder of the central nervous system characterized by unwanted choreatic movements, behavioral and psychiatric disturbances and dementia. "Conversely, NLK overexpression reduces toxicity in Huntington’s disease models, indicating context-dependent effects of NLK in neurodegeneration." (PMID 40553568, 2025). "Moreover, NLK can regulate neurodegenerative diseases, such as Huntington’s disease and spinocerebellar ataxias." (PMID 33276680, 2020). "Furthermore, NLK could conduct the function and differentiation of cells from the immune system, in addition to regulating neurodegenerative diseases, such as Huntington’s disease and spinocerebellar ataxias." (PMID 33276680, 2020).
leukemia (2 papers, 2021 to 2024). A malignant (clonal) hematologic disorder, involving hematopoietic stem cells and characterized by the presence of primitive or atypical myeloid or lymphoid cells in the bone marrow and the blood. "The qRT-PCR and ELISA results of this study reflected that the hub genes RHOA, RYK, NLK and MHC-I molecules HLA-A of the atypical Wnt signaling pathway were down-regulated in leukemia cells." (PMID 38962268, 2024).
liver cancer (2 papers, 2015 to 2021). An epithelial or non-epithelial malignant neoplasm that arises from the liver. "In liver cancer, miR-101 targets nemo-like kinase (NLK) and plays an inhibitory role by inhibiting NLK activity." (PMID 34659567, 2021).
lymphoma (2 papers, 2017 to 2021). A malignant (clonal) proliferation of B- lymphocytes or T- lymphocytes which involves the lymph nodes, bone marrow and/or extranodal sites.
myocardial infarction (2 papers, 2016 to 2021). Gross necrosis of the myocardium, as a result of interruption of the blood supply to the area, as in coronary thrombosis. "Here we identified NLK as a gene product induced in the hearts of mice subjected to pressure overload or myocardial infarction injury, suggesting a potential regulatory role with pathological stimulation to this organ." (PMID 27764156, 2016). "We suspected that NLK might play a regulatory role in the heart given an observed upregulation of its expression following 2 weeks of pressure overload hypertrophy induced by transverse aortic constriction (TAC) and 1 week after myocardial infarction (MI) injury." (PMID 27764156, 2016).
Obesity (2 papers, 2015 to 2016). Accumulation of substantial excess body fat. "Polymorphisms of NLK were strongly associated with obesity in human and fatty acid composition in pig." (PMID 28030618, 2016). "Brain transcriptome analyses in obese mice identified several obesity-related pathways (e.g. leptin, somatostatin, and nemo-like kinase signaling), as well as genes involved in feeding and appetite (e.g. Pmch, Neurotensin) and in metabolism (e.g. Bmp4, Bmp7, Ptger1, Cox7a1)." (PMID 25629159, 2015).
pancreatic cancer (2 papers, 2019 to 2024). "To further verify the regulation of MSI2 and NLK on pancreatic cancer cells in vivo, we performed nude mouse transplantation tumor experiments." (PMID 39097735, 2024). "In vitro and in vivo experiments were conducted to investigate the role and mechanism of MSI2 in promoting malignant behaviors of pancreatic cancer through regulation of NLK." (PMID 39097735, 2024). "NLK, as an evolutionarily conserved serine/threonine protein kinase activated during mitosis, has been found to promote or inhibit different tumors, and its role in pancreatic cancer is still unclear." (PMID 39097735, 2024). "Through in vivo and in vitro experiments, we revealed that MSI2 directly binds to the NLK mRNA to maintain its stability and promote the invasion and migration of pancreatic cancer cells, and NLK promotes pancreatic cancer progression through the EMT and PI3K/AKT/mTOR signaling pathway." (PMID 39097735, 2024). "The regulation of PI3K/AKT/mTOR signaling by MSI2 and NLK in pancreatic cancer is still unclear." (PMID 39097735, 2024). "The mRNA levels of NLK showed the most significant changes in response to MSI2 knockdown and overexpression in pancreatic cancer cell lines, as observed in Capan-2 cells (MSI2-Ctrl VS MSI-Sg) and Panc-1 cells (Lv-Vector VS Lv-MSI2)." (PMID 39097735, 2024). "Our results demonstrate that NLK can promote the occurrence and development of EMT in pancreatic cancer cells." (PMID 39097735, 2024). "The high expression of NLK activates the PI3K/AKT/mTOR and EMT signaling pathways, promoting the invasion and migration of pancreatic cancer cells." (PMID 39097735, 2024). "This study is the first to report the role of NLK in the progression of pancreatic cancer and confirms that MSI2 promotes pancreatic cancer development and affects prognosis by directly binding to NLK." (PMID 39097735, 2024). "Immunohistochemical results showed that MSI2 is primarily expressed in the cytoplasm, while NLK is expressed in both the cytoplasm and the nucleus of pancreatic cancer cells, and there is close correlation between MSI2 and NLK expression." (PMID 39097735, 2024). "The expression levels of NLK and MSI2 in pancreatic cancer tissues in nude mouse were verified by Western Blot." (PMID 39097735, 2024). "Currently, there are no reports on the expression of NLK in pancreatic cancer and its relationship with prognosis." (PMID 39097735, 2024). "Our study confirmed that overexpression of NLK increased the expression of p-PI3K (Tyr458), p-AKT (Ser473), and p-mTOR (Ser2448) in vitro, while knockout of NLK suppressed the PI3K/AKT/mTOR signaling pathway and inhibited EMT in pancreatic cancer cell lines." (PMID 39097735, 2024). "Building on our previous research, this study further confirms that MSI2 can affect EMT by regulating NLK, and both of them together promote the deterioration of the prognosis of pancreatic cancer patients, which also provides a potential target for EMT-targeted therapy in pancreatic cancer." (PMID 39097735, 2024).
spinocerebellar ataxia 1 (2 papers, 2015 to 2025). "Previous studies have shown that NLK is able to modulate the development of spinocerebellar ataxia type 1, which suggests that NLK may also play an important role in other polyglutamine diseases." (PMID 26308581, 2015).
astrocytoma (1 paper, 2015). "Interestingly, introduction of the HOTAIR 5′ domain into an astrocytoma-derived primary culture dramatically decreased NLK expression, whereas the HOTAIR 3′ domain did not have this effect." (PMID 25823657, 2015).
benign breast disease (1 paper, 2013). "The results of these experiments indicated that mammary epithelial and myoepithelial cells from benign breast disease samples showed strong immunoreactivity for NLK in the nucleus, with weak to no c-Myb staining." (PMID 23935942, 2013).
brain injury (1 paper, 2016). Acute and chronic (see also brain INJURIES, CHRONIC) injuries to the brain, including the cerebral hemispheres, CEREBELLUM, and brain STEM. "A previous study also demonstrated that NLK was involved in neuronal apoptosis after traumatic brain injury." (PMID 27776139, 2016).
cardiac hypertrophy (1 paper, 2016). "Nlkfl/fl-βMHC-Cre mice deficient in NLK protein showed significantly less cardiac hypertrophy and a resistance against heart failure as suggested by a reduction in FS compared with Nlkfl/fl control mice subjected to 2 weeks of TAC." (PMID 27764156, 2016). "NLK transgenic mice demonstrated baseline cardiac hypertrophy, dilation, interstitial fibrosis, apoptosis and progression towards heart failure in response to two surgery-induced cardiac disease models." (PMID 27764156, 2016). "NLK DTG mice also had increased heart/body weight ratios as well as an increase in the cross-sectional area of individual cardiomyocytes within their heart, indicating cardiac hypertrophy." (PMID 27764156, 2016).
cardiomyopathy (1 paper, 2016). A disease of the heart muscle or myocardium proper. "Here we determined that mice with inducible and cardiac-specific expression of NLK develop baseline cardiomyopathy and are more susceptible to heart failure upon pressure overload, as well as to greater myocyte death with I/R injury." (PMID 27764156, 2016).
cerebral amyloid angiopathy (1 paper, 2025). "Most AD patients are reported to have some degree of cerebral amyloid angiopathy, for which NLK is a potential biomarker." (PMID 40471493, 2025). "High levels of NLK may therefore indicate both existing vascular amyloid depositions and cerebral amyloid angiopathy." (PMID 40471493, 2025).
Chronic colitis (1 paper, 2019). A chronic inflammatory disease of the large intestine (colon, cecum and rectum). "The results showed that SSW inhibited activation of downstream proteins of the NEMO/NLK signaling pathway in TNBS-induced chronic colitis." (PMID 30894816, 2019).
diabetes (1 paper, 2021). "Despite there being no specific small-molecule inhibitor of NLK activity, the commonly prescribed diabetes drug, metformin, has demonstrated efficacy in downregulating NLK expression and improving erythropoiesis in human, mouse, and animal models of DBA." (PMID 34298020, 2021).
Fanconi Anaemia (1 paper, 2022). "In addition, the top two enriched KEGG pathways were: 1) the Fanconi Anaemia pathway (represented by ATR, BRIP1, ERCC4, FANCC and POLH) and the FoxO signalling pathway (represented by CREBBP, NLK, PRKAA2, PRKAB1, PTEN and STK11)." (PMID 35768547, 2022).
heart failure (1 paper, 2016). Inability of the heart to pump blood at an adequate rate to meet tissue metabolic requirements. "Mechanistically, overexpression of NLK was a potent pathological effector in the hearts of transgenic mice, while its deletion specifically from myocytes of the heart protected against progression towards heart failure following pathologic stimuli." (PMID 27764156, 2016).